IL10 (interleukin 10)
Diseases named in the same sentence as IL10 in open-access papers (continued):
Sharing a sentence is not in itself a finding about the gene and the disease.
cancer (continued). "Scattered reports show that administration of pegylated recombinant human IL-10 triggered immune activation in cancer patients with encouraging results in cancer control." (PMID 37215142, 2023). "Our observations have suggested that MDSC secreted IL-10/IL-6/IL-1β are the critical players modulating the drug resistance of cancer cells via STAT3/STAT1/NF-κB pathway." (PMID 38304256, 2023). "Many well-known proteins that play crucial roles in cancer like IL10, USP18, and IL22 were included in this network." (PMID 37697300, 2023). "By contrast, the positive correlation between cancer and IL-10 has attracted considerable interest, and IL-10 is considered a cancer biomarker and target for the development of cancer therapies." (PMID 38102207, 2023). "Out of the soluble factors, IL10 is an important anti-inflammatory cytokine that is markedly increased in ascites from OC patients and helps in cancer cell migration and proliferation." (PMID 38264664, 2023). "Studies in the literature demonstrate that most of the work has been conducted on the effect of proinflammatory cytokine IL-10 genomic variations on various cancers including hematological malignancies." (PMID 37232720, 2023). "Further understanding of IL-10's role in cancer development can aid us in new cytokine immunotherapies in malignancies." (PMID 37501757, 2023). "IL-10 is a vital immunosuppressive cytokine that is generally overexpressed in tumors and protects cancer cells from immune-mediated destruction." (PMID 37893013, 2023). "Future directions in cancer immunotherapy should focus on counteracting IL-10’s immunosuppressive effects." (PMID 37454231, 2023). "MDSCs from patients with cancer express higher ARG‐1, IDO, IL10, and iNOS expression was higher in MDSCs from patients with cancer than from healthy donors." (PMID 37547175, 2023). "IL-10 and TGF-β are abundance in cases of chronic infections or cancer, and attenuation of IL-10 and TGF-β signaling contributes to the prevention and reversal of T-cell exhaustion." (PMID 37582972, 2023). "IL-10+ regulatory B cells (Bregs) play a significant role in cancer immunotherapy and their presence is an indicator of negative outcome." (PMID 37291146, 2023). "For example, butyrate is reported to induce IL-10 and IL-18 production through GPR109A to inhibit colonic inflammation and inflammation-associated cancers." (PMID 37238867, 2023). "Recently, increasing evidence has proven that IL-10 induces antitumor activity increasing CD8+ T lymphocyte activation in immunologically “cold” cancers." (PMID 37483629, 2023). "Accordingly, supernatant secreted from MDSCs induces a surge of receptor expression for IL-6, IL-10 and IL-1β in cancer cells." (PMID 38304256, 2023). "PD-1 and IL-10 pathways are upregulated in chronic infections and cancers as a result of antigen persistence, impairing immunity and advancing disease." (PMID 37153623, 2023). "Many studies have proved that IL-10 derived from cancer can activate MDSCs through STAT3 pathway, and in our study, we found that MDSCs are accompanied by a large amount of IL-10 secretion in the process of inducing B10 cell differentiation." (PMID 35725835, 2023). "Inflammation has arisen as a viable cause both in CV disease and cancer, because correlation between tumour biomarkers and proinflammatory cytokines, such as TNF-α, IL-6 and IL-10, has been identified." (PMID 36830690, 2023). "The anti-cancer effects of carnosine on U937 cells stem from the simultaneous increased expression of IL-1β, increased secretion of IL-10, GM-CSF, and TNFα, and decreased secretion of IL-8." (PMID 37998326, 2023). "Supernatant from bone marrow derived MDSCs of IL-10-/- mice exposed to cancer cells (EP, LP) revealed a substantial reduction in the expression of Pgp than wild type, validating the role of IL-10 in generation of drug resistant cancer cells." (PMID 38304256, 2023).
cancer (continued). "Our positive results highlight the potential for the development of such an antibody-IL-10 fusion protein as a promising strategy against TAM-enriched cancers." (PMID 37586318, 2023). "Factors that decrease immune function (e.g., PD-L1, CTLA-4, and IL-10) are significantly increased in the immune and cancer cells in cancer tissues." (PMID 37153541, 2023). "More importantly, we also found that increased MDSCs accumulation, IL-10 or BAFF expression independently correlates with shorter survival in cancer patients, which was supported by TIMER and GEPIA database." (PMID 35725835, 2023). "Conversely, mammalian target of rapamycin (mTOR) inhibitors, such as sirolimus, reduce the incidence of cancer by suppressing p70 S6K, interleukin-10, and cyclin; downregulating VEGF; and inducing apoptosis." (PMID 38269025, 2023). "TAMs, cancer-associated fibroblasts, and immunosuppressive cytokines in TME, such as TGF-β or IL-10, induce T cell exhaustion." (PMID 36721212, 2023). "Studies have also demonstrated that IL-10 stimulates the epithelial-mesenchymal transition (EMT) process in cancer cells and enhances cancer cell proliferation through the STAT3-NF-κB-IL-10 signaling axis." (PMID 37637038, 2023). "Pro-tumorigenic cytokines secreted by neutrophils and platelets (vascular endothelial growth factor, tumor necrosis factor-α, interleukin-10, etc.)contribute to cancer progression." (PMID 36979727, 2023). "On the other hand, interleukin-10 (IL-10) is an immunosuppressive cytokine that can stimulate cancer growth by helping the malignant cells escape the immune response." (PMID 37189693, 2023). "The cytokines IL-6 and IL-10 are important for Th2-mediated function in cancer progression and exhibited reduced levels in the low-dose SNAP treatment group." (PMID 36639681, 2023). "Conglomeration of all our observations has suggested that MDSC secreted IL-6/IL-10/IL-1β are the supreme players regulating the drug resistance of cancer cells via STAT1/STAT3/NF-κB pathway." (PMID 38304256, 2023). "In contrast to cytokines, whose increased levels have been associated with both CV disease and cancer, there are some cytokines, such as IL-10, that play a role in the development of cancer, but with protective effects in CV diseases." (PMID 36830690, 2023). "In return, the overexpression of Notch1/2 suppresses the expression of TLR4-induced proinflammatory cytokines, TNF-α, and IL-6 and favor cancer-promoting anti-inflammatory cytokine IL-10." (PMID 36765706, 2023). "Pegylated IL-10 was well tolerated in cancer clinical trials, which showed induction of CD8+ T cell immunity." (PMID 37586318, 2023). "Although the role of B cells in human cancer immunity and immunotherapy remains poorly understood, the presence of IL-10+ Bregs in human cancers was reported previously, and their presence was found, for some cancer types, to be an indicator of poor prognosis." (PMID 37291146, 2023). "In cancer cells, miR-30d-5p induces IL-10 expression (an immunosuppressive cytokine), at least in part by repressing the GALNT7 gene, resulting in pro-metastatic effects in vivo." (PMID 36960962, 2023). "The M2-like TAMs then facilitated cancer cell escape by secreting high levels of IL-10, VEGF, PGE2, and MMP-9." (PMID 37210553, 2023). "The anti-inflammatory cytokine IL-10 has been considered a potential therapeutic target and tested in different clinical trials for multiple diseases such as cancer, autoimmune, and neurodegenerative diseases." (PMID 37513979, 2023). "For the part of inflammation in cancer, the following keywords were used: cytokines in cancer, inflammation in cancer, IL-6 in cancer, IL-10 in cancer, and TNF-α in cancer." (PMID 36771154, 2023). "Different cytokine-related pathways were upregulated in the stroma during the progression from normal mucosa to carcinoma, including interferon γ, interleukin (IL)-11, IL-10, IL-6, IL-9, IL1R and IL-18 signalling pathways." (PMID 36442992, 2023).
cancer (continued). "IL22RA1 was positively correlated with STAT1, STAT3, JAK1, PTPN11, IFNA13, IL24, but negatively correlated with IL10 in specific cancers." (PMID 35874683, 2022). "Cancer cell-derived osteopontin (OPN), a glyco-phosphoprotein involved in cell adhesion, chemotaxis, macrophage-directed interleukin-10 suppression, and prevention of cellular apoptosis, is a marker for aggressive cancer growth." (PMID 36284815, 2022). "By producing cytokines, including TNF-α, IL-12, and IL-6, M1 macrophages have an anti-cancer effect, but M2 macrophages promote the proliferation of cancer cells by producing IL-10, TGF-α." (PMID 36298592, 2022). "As TGFβ1, TEV enriched in IL-10 were detected in plasma of different cancer patients; however, the most relevant action performed by TEV is the induction of IL-10 and TFGβ1 in target cells via their RNA content." (PMID 36011012, 2022). "Like IL-8, the immunosuppressive cytokine IL-10 is abundantly expressed in TAMs, promoting cancer cell proliferation and metastasis." (PMID 35955737, 2022). "These B regulatory cells characterized by IL10 production (Breg) have been shown to interfere with the immune response in several diseases, including cancer." (PMID 35741714, 2022). "In concurrence with the clinical reports from cancer patients, we similarly observed an increase in IL-10 levels after PTX dosing." (PMID 35273508, 2022). "Based on different models of murine cancer, numerous reports have shown that the upregulation of Wnt ligands produce IL-10 in tumors program dendritic cells, which contributes to the immune inhibition through promoting T regulatory cell responses." (PMID 36437782, 2022). "Alternatively, TME promotes the polarization of TAMs into macrophages M2 with anti-inflammatory and cancer-promoting properties, which produce IL-10 and suppress CD8+ T cell responses." (PMID 36139065, 2022). "It was found that IL-10 concentration in cancer patients’ blood correlated with overall survival, as well as the level of TGFβ was also frequently elevated in patients with high IL-10." (PMID 36140243, 2022). "Numerous cytokines such as IL-6, IL-10, IL-23, TNF-α, and TGF-β were found to be associated with carcinogenesis and the development of cancers, functioning as pro- or anti-tumorigenic." (PMID 36140470, 2022). "Among the cancer-produced immunosuppressive cytokines, IL-10 is responsible for the overexpression of HLA-G, which is implicated in the immune escape." (PMID 36437782, 2022). "To explore the effect of TAMs on cancer cell behaviors, we generated M2 macrophages from U937 cells by treatment with IL-4/IL-10 and HCC cells/U937 cells coculture CM, named M2 MφsCyto and TAMsCM, respectively." (PMID 36411463, 2022). "As well, in the occurrence and development of cancer, IL-10 promotes the growth and proliferation of cancer cells." (PMID 36185234, 2022). "Pro-tumorigenic cytokines secreted by neutrophils and platelets, including vascular endothelial growth factor, tumor necrosis factor-α, and interleukin-10, can contribute to cancer progression." (PMID 35006344, 2022). "The more IL10, the more removal of cytotoxic cells and hence less death of cancer cells by cytotoxic cells." (PMID 35294447, 2022). "The systemic inflammatory response of cancer prompts neutrophil infiltration, resulting in the secretion of interleukin-2 (IL-2), interleukin-6 (IL-6), interleukin-10 (IL-10), tumor necrosis factor α (TNF-α), and vascular endothelial growth factor (VEGF)." (PMID 35407463, 2022). "The β-GBP promotes secretion of IL-10 and IL-35 impairing T cell effector function and promoting proliferation of cancer cells." (PMID 36338731, 2022). "The key THαβ cytokine, IL-10, potently inhibits cancer cells in vitro and suppresses cancers in vivo." (PMID 36289759, 2022). "A meta-analysis of 1788 cancer patients also revealed that the elevated serum IL-10 can predict poor prognosis." (PMID 35784354, 2022).
cancer (continued). "Various other cytokines are believed to be involved in the metastasis and progression of several cancer types through similar pro-inflammatory activity, including IL-4, IL-8, IL-10, and TGF-β." (PMID 35565306, 2022). "MET bidirectionally regulates both cancer cells and different immune cells, and MET expression in monocytes/macrophages/neutrophils was associated with IL-10 expression and immunosuppressive myeloid cells." (PMID 36230855, 2022). "Cancer immune evasion can be due to functional and structural modifications of HLA-class I molecules and/or the detrimental activity of immunosuppressive cytokines, including IL-10, which is recognized as one of the hallmarks of cancer." (PMID 36437782, 2022). "IL10 is produced proportional to the number of dendritic cells, macrophages, cytotoxic, helper, and regulatory T-cells plus cancer cells and decays naturally." (PMID 35294447, 2022). "The Siglec-9 expressed on this cell can bind to the Mucins1-related STn antigen released by cancer cells and lead to an increase in interleukin-10 and a decrease in the production of IL-12." (PMID 36245971, 2022). "For the analysis of 24 immune-inhibiting genes, we found that SERPINH1 expression was highly associated with CD276, TGFBI, VEGFA, HAVCR2, IL10, and ADORA2A in most cancers." (PMID 36105106, 2022). "Particularly, TGF-β and IL-10 drive a shift from the Th1-type response toward the Th2-type response, leading to cancer immune evasion." (PMID 36726985, 2022). "Because of its pro-inflammatory effects on the expansion and activation of primed CD8+ T cells and natural killer cells, IL-10 has been explored as an immuno-oncologic agent for treating cancer." (PMID 35795558, 2022). "Concurrently, factors, such as interleukin (IL)-10 secreted by cancer or interstitial cells, are also important in the differentiation from monocytes to macrophages rather than to dendritic cells." (PMID 36362044, 2022). "And some studies reported the high IL-10 expression levels in the BC paraffin section and its expression is correlated with worse outcomes in patients with malignant tumors." (PMID 35186043, 2022). "In ovarian cancer TFH cells PD‐1+ presented higher IL‐21 and IL‐10 secretion and stronger proliferation from non‐cancer (NC) controls." (PMID 35344301, 2022). "Previous reports showed that PD-L1 can be induced in MDS cells by IFNγ and TNFα, although a variety of other factors (i.e., IL-10, FasL, and IL-17A) have been shown to upregulate PD-L1 in other cancer types." (PMID 35992887, 2022). "Chronic systemic inflammation mediated by cancer-induced cytokines (IL-6, IL-10) is reflected in the increase in the number of circulating platelets." (PMID 35268305, 2022). "This is because macrophages produce IL6 and IL10, promoting cancer proliferation and inhibiting cytotoxic T cell proliferation." (PMID 35629230, 2022). "IL-10 plays an important role in the pathogenesis of cancer: the excessive production of IL-10 increases the likelihood of tumors due to immunosuppression." (PMID 36286034, 2022). "For Mouse 2, the parameter λIL10C promotes the production of IL10, which can affect cancer through cytotoxic cells." (PMID 35294447, 2022). "Cancer-associated fibroblasts- (CAF-) educated cells inhibited T cell proliferation through the production of TGFβ and IL-10 and facilitated an immunosuppressive microenvironment." (PMID 39280892, 2022). "Foxp3+ regulatory T cells (Tregs) are a subset of CD4+ T cells that originate in the thymus or are activated locally by TGFβ, IL-10, or IL-2, and are implicated in the TME of numerous cancers." (PMID 36140470, 2022). "Previous research has indicated that IL10 was reported to be upregulated in numerous advanced cancers, confirmed by the present work." (PMID 36389789, 2022). "These inconsistent studies on IL-10 suggest that the cellular source of IL-10 and the effects of IL-10 on different cell types are what determine the ultimate role of IL-10 in cancer." (PMID 36091125, 2022).
cancer (continued). "The N1 phenotype with high levels of TNF-α, IL-2, IL-4, IL-7, and IL-10 expression induces a cytotoxic effect to cancer cells and hampers cancer cell progression." (PMID 35267547, 2022). "This subset showed high activity of angiogenesis, hedgehog signaling, epithelial mesenchymal transition, NF-κB pathway, and IL10 signaling, suggesting it had essential roles in the remodeling of cancer immunity and progression." (PMID 35664061, 2022). "Like their autoimmune counterparts, IgA+ Bregs in cancer suppress T cells and macrophages by IL-10- and PD-L1-mediated mechanisms." (PMID 35350071, 2022). "IL10 was expressed by malignant tumor cells, inhibiting various immune-related cell populations to achieve immune escape, while the rise of IL6 occurred in inflammation indicated stronger immune response." (PMID 35186744, 2022). "In the immune microenvironment of CCA, cancer cells and stromal cells such as TAMs, TANs, MSDCs and CAFs inhibit the immune protection function of TILs by secreting factors like IL-10 and TGF-β." (PMID 35392957, 2022). "Genes of the Interleukin 10 (IL-10) family play a dual, contentious function in a variety of cancers." (PMID 36339551, 2022). "IL10 is thought to have the ability to suppress antitumor T cell responses in cancer, but several researches have also suggested that IL10 took part in some inherent antitumor T cell responses." (PMID 35909123, 2022). "Bidirectional crosstalk between TAMs and cancer cells promotes TAMs to secrete IL-8 and IL-10 into the TME, resulting in the tumorigenesis, metastasis, and angiogenesis of solid cancers." (PMID 35955737, 2022). "When more SP is released, it can decrease the apoptosis subsequently by modulating the immune markers IL4, IL6, and IL10, resulting in unrestrained cell division, cell progression, and prominent cancer metastasis." (PMID 34692834, 2021). "This dual part played by IL-10 suggests its role in coming up with improved and advanced anti-cancer vaccines." (PMID 34336101, 2021). "Tregs are a major barrier to antitumor immunity in various cancers; for instance, they secrete immunoregulatory cytokines, including IL-10 and TGF-β." (PMID 34649584, 2021). "The pathway downstream of IL-10 includes Janus kinase and STAT, indicating that IL-10 promotes cancer progression and metastasis in the same way as IL-6." (PMID 33578830, 2021). "A meta-analysis comprising 1788 patients with cancer demonstrated that high levels of IL-10, in serum, are correlated with a lower overall survival (OS) both in solid cancers and hematological malignancies." (PMID 34832887, 2021). "They assessed the effects of TNF blockade and genotoxin colibactin-producing (clb+) E. coli in a model of colitis-associated cancer using DSS/Apcmin/+ mice and Apcmin/+; Il10−/− mice." (PMID 33578830, 2021). "IL-10 is an anti-inflammatory cytokine that plays a critical role in the control of immune responses in both inflammation and cancer." (PMID 34930387, 2021). "While IL-4, IL-5 and IL-13 have been documented to contribute to cancer growth and metastasis, a dual pro- and anti-tumorigenic role of IL-10 has been reported in recent literature, as reviewed elsewhere." (PMID 34012451, 2021). "Further studies revealed that CD45+ EPCs induced by cancer use multiple additional immunoregulatory mechanisms, including IL-10, TGF-β, and PD-1/PD-L1." (PMID 33669537, 2021). "Although IL-10 is generally considered an immunosuppressive cytokine, its role in cancer is controversial." (PMID 33578830, 2021). "SCFAs promote Treg development, which in turn secrete IL10 secretion/ IL-10 impairs the anti-cancer activity of Th1 cells and therefore promotes cancer development." (PMID 34683450, 2021). "In cancer biology, the exact role of IL-10 is insufficiently clear and both pro-tumorigenic and anti-tumorigenic functions have been described." (PMID 33679785, 2021).